CSF1R (colony stimulating factor 1 receptor)
Diseases named in the same sentence as CSF1R in open-access papers (continued):
Sharing a sentence is not in itself a finding about the gene and the disease.
cancer (391 papers, 2007 to 2026). A tumor composed of atypical neoplastic, often pleomorphic cells that invade other tissues. "Current research is now focused on strategies to overcome stromal barriers and to “reprogram” or deplete immunosuppressive cell populations within the TME, such as using CD40 agonists, CSF-1R inhibitors, or therapies targeting cancer-associated fibroblasts." (PMID 41331510, 2025). "CSF1R is overexpressed or mutated in breast, as well as other cancer types, correlating with disease progression and malignancy." (PMID 39625569, 2025). "In a CSF-1R-overexpressing MCF-7 cancer cell line, CSF-1 induced cell cycle arrest associated with increased p21 levels and the formation of p21/CDK complexes preventing cell cycle progression." (PMID 38254773, 2024). "Studies have shown that high expression of CSF-1 or CSF-1R is associated with poor prognosis in some malignant tumors, such as Hodgkin’s lymphoma and hepatocellular carcinoma." (PMID 39403370, 2024). "Among them, cancer-associated fibroblasts (CAFs), endothelial cells (ECs), and cancer stem cells (CSCs) express the CSF-1R and exhibit responsiveness to its regulatory signals." (PMID 39457693, 2024). "In this study, we found that FAP expression was positively correlated with the infiltration of cancer associated fibroblasts, macrophages, as well as CSF1R protein in most cancers." (PMID 37166418, 2023). "It was reported that the expression of CSF-1R was associated with poor prognosis in certain cancers." (PMID 37923984, 2023). "This was because apart from macrophages, CSF1R signals in cancer-associated fibroblasts leading to macrophage inflammatory protein 2 secretion triggered the manifestation of suppressive and angiogenic properties in macrophages upon CXCR2 paracrine activation." (PMID 35315360, 2022). "In particular, we demonstrated that the ligand-activated CSF-1R increased the expression of spp1 transcript encoding for osteopontin, a key player in cancer development and metastasis." (PMID 36555673, 2022). "Unlike WT littermates or monocytes from Mb1-CSF1RFlox/Flox mice, the loss of CSF1R in BMBP significantly impaired the cancer CM-induced B-MF differentiation." (PMID 36104343, 2022). "As the presence of TAMs is associated with poor prognosis in many cancer types, therapies that modulate CSF1R signaling have garnered attention." (PMID 35107133, 2022). "In various cancers, such as pancreatic and breast, cancer-associated MDSCs express high levels of surface CSF-1R which is responsible for immunosuppressive effects through inhibition of T cell activity." (PMID 35127700, 2021). "Accordingly, in different cancer types, CSF-1R blockade has been found to be associated with TAM reprogramming in antitumor effectors." (PMID 33922336, 2021). "Prior studies showed cancer patients harboring germline CSF1R c.1085A>G genetic variant had better survival." (PMID 34830445, 2021). "High carcinoma CSF-1R was significantly associated with poor survival in univariate and multivariate analyses." (PMID 34830923, 2021). "Together, these results show a negative prognostic association linked with the concurrent expression of CSF-1R+ carcinoma cells and CSF-1R+ macrophages in ER-positive breast cancers." (PMID 34830923, 2021). "The subsequent multivariate analysis confirms that high CSF-1R expression on carcinoma cells is independently associated with unfavorable outcome (HR 1.58; 95% CI 1.21–2.05; p = 0.001)." (PMID 34830923, 2021). "Together, these results suggest an association of CSF-1R+ carcinoma cells in supporting an immune-suppressed microenvironment." (PMID 34830923, 2021). "Our results show that high CSF-1R expression on carcinoma cells is associated with significantly inferior survival in cases harboring CD8+ iTILs (HR 1.65, 95% CI 1.21–2.26; p = 0.002)." (PMID 34830923, 2021).
cancer (continued). "We found that CSF-1R+ carcinoma cells are associated with significantly adverse outcome in patients with ER-positive status (HR 1.82, 95% CI 1.30–2.54; p < 0.001) but not in those with ER-negative status (HR 1.08, 95% CI 0.73–1.60; p = 0.71)." (PMID 34830923, 2021). "Accordingly, targeting TAMs via the CSF1/CSF1R or CX3CL1/CX3CR1 signaling pathway is an attractive therapy for cancers associated with increased numbers of TAMs (reviewed in refs.46,47)." (PMID 30237497, 2018). "In another study of Hodgkin's lymphoma, all cancer patient samples were found to have alternative transcripts of the CSF1R, an important locus associated with this cancer, that initiate at the LTR of an ERV located ~6.2 kb upstream of the normal promoter." (PMID 28439515, 2017). "Indeed, the loss of miR-34a and the increased expression of the CSF-1R increases cancer cell stemness, supported by the increased expression of stem cell markers, including Lrg5 and OLFM4." (PMID 39457693, 2024). "In addition, cancer cells possess mutations in the extracellular region of the receptor, leading to the constitutive expression of the CSF-1R and the sustained activation of its tyrosine kinase activity." (PMID 39457693, 2024). "The overexpression of CSF1R has been associated with poor prognosis in many cancers and accumulated evidence has made it clear that combination of CSF1R immunotherapy with other standard-of-care often improves therapeutic response which is currently of clinical interest." (PMID 33986740, 2021). "Indeed, CSF1R inhibition has been reported to trigger an increase of granulocyte-specific chemokines produced by cancer-associated fibroblasts, resulting in an influx of granulocytes into tumors." (PMID 34201127, 2021). "However, the association between CSF1R c.1085 genotype and clinical outcome of cancer patients was rarely reported." (PMID 34830445, 2021). "We observed that in ER-positive cases, concomitant high expression of CSF-1R on carcinoma cells and macrophages is associated with significantly poorer clinical outcome (HR 1.57, 95% CI 1.13–2.17; p = 0.006), compared to ER-negative cases (HR 1.09, 95% CI 0.75–1.57; p = 0.66)." (PMID 34830923, 2021). "These cancers are associated with shorter progression-free survival, Gleason scores ≥ 7, and an immunosuppressive environment defined by a higher proportion of PD-1, PD-L1 and colony-stimulating factor 1 receptor (CSF1R) positive cells." (PMID 31431617, 2019). "The pathogenesis of several malignant tumors is associated with overexpression of CSF1R and PDGFRB." (PMID 21171987, 2010). "However, the CSF-1R signaling axis also influences other immune and non-immune subsets, including dendritic cells, neutrophils, and cancer-associated fibroblasts, which may either augment or neutralize the effects of CSF-1R inhibition." (PMID 34830923, 2021). "Thus, 3D185 could maximize the therapeutic potential against the targets FGFR and CSF-1R in cancer patients and avoid the classic toxic effects associated with KDR." (PMID 31438996, 2019). "In particular, the interactions between interleukin‐34 (IL34) and its receptor, colony stimulating factor‐1 receptor (CSF1R), have emerged as key modulators of immune responses in various cancers." (PMID 41362277, 2026). "It has been previously shown that activation of the CSF-1/CSF-1R signaling pathway and overexpression of CSF-1R promote PC progression and increase the expression of the SPP1 transcript encoding osteopontin, a key factor in cancer development and metastasis." (PMID 39941714, 2025). "Several clinical trials tested the beneficial use of CSF1R inhibitors in combination with immunotherapy, targeted therapy, or chemotherapy in different types of cancer." (PMID 40538439, 2025). "Some cancers, including orthotopic glioblastoma and localized prostate cancer, are now undergoing clinical studies that combine chemotherapy with CSF1R inhibitors." (PMID 40422244, 2025).
cancer (continued). "This context-dependency also extended to molecules like TNFRSF14 (HVEM), CSF1R, and several HLA genes, which were positively correlated in cancers like COAD and LIHC but negatively correlated in ESCA, LGG, and LUSC." (PMID 41614761, 2025). "Ultimately, the combination of imaging biomarkers with immunotherapeutic strategies, e.g., CSF-1R inhibitors, holds the promise of achieving more precise and individualized cancer management." (PMID 40725764, 2025). "Various CSF1R inhibitors have been recently developed to target CSF1R signaling, fueled by their therapeutic potential in cancer treatments." (PMID 39448548, 2025). "Recently, the promising therapeutic potential of CSF-1/CSF-1R signaling pathway inhibition in cancer treatment is widely used." (PMID 40007537, 2025). "CSF1R inhibition effectively depletes pathogenic macrophages in cGVHD, while STAT3/IDO modulation enhances monocyte‐derived dendritic cell activation for cancer immunotherapy." (PMID 40936181, 2025). "TRAP-seq identified oxidative phosphorylation/glycolysis as anti-CSF1R therapy resistance mechanism, and it’s combined with Cancer Therapeutics Response Portal (CTRP) identified piperlongumine (PL) or vorinostat (SAHA) as targeting drugs." (PMID 41365876, 2025). "Given that the survival and proliferation of microglia and macrophages depend on the CSF1R signaling pathway, several CSF1R inhibitors have been developed as potential therapies for neurological disorders and cancer." (PMID 40360942, 2025). "In clinical studies, LY3022855, a CSF-1R inhibitor, reduced TAMs and raised pro-inflammatory cytokines, but it had a limited anti-cancer effect, with some patients having stable illnesses." (PMID 40422244, 2025). "Targeting colony-stimulating factor 1 (CSF1) and CSF1 receptor (CSF1R) for M2 macrophage reprogramming has been widely implemented in clinical trials for cancer therapy." (PMID 40821781, 2025). "Targeting the CSF-1/CSF-1R signaling pathway to disrupt CSF-1R expression has demonstrated significant therapeutic potential across various cancers." (PMID 40850976, 2025). "CSF1R inhibitors have emerged as promising immunomodulatory agents in cancer therapy, primarily due to their ability to target TAMs and MDSCs." (PMID 40821795, 2025). "By employing CRISPR screening in CAR-macrophage and cancer cell co-culture system, the authors identify depletion of ATG9A on cancer cells sensitizes them to macrophage-mediated killing, which can be synergic with CSF1R inhibition in cancer treatment." (PMID 40595560, 2025). "Here, using a validated mouse model for preclinical studies of RCC, the upregulation of IL34 in cancer cells led to the accumulation of monocyte-derived TAMs through CSF1R." (PMID 40538439, 2025). "Chemorefractory cancer cells recruit TAMs via the CSF-1R, further enhancing PD-L1 expression through TGF-β signaling, thereby creating an immunosuppressive TME resistant to chemotherapy." (PMID 39457693, 2024). "Since recent research has demonstrated its expression also on the surface of cancer cells, the relevance of CSF-1R in this field has increased." (PMID 38254773, 2024). "CSF-1, a major growth and differentiation factor released by cancer cells, interacts with its cognate receptor, CSF-1R, which is widely expressed by macrophages and monocytes." (PMID 39403370, 2024). "The aim of this review is to gather available data on CSF-1R expression in cancer cells to provide a new way to consider this receptor." (PMID 38254773, 2024). "Clinical trials across various cancer types have explored drugs that inhibit this CSF-1/CSF1-R pathway, utilizing both monoclonal antibodies and small-molecule inhibitors." (PMID 39766202, 2024). "In the context of gastric cancer, multiple clinical trials involving patients are underway to investigate the clinical efficacies of CSF-1R inhibitors in cancer treatment." (PMID 39003350, 2024). "In this review, we summarize the evidence of CSF-1R expression in cancer tissue and cancer cell lines." (PMID 38254773, 2024).
cancer (continued). "The macrophage growth factor Colony Stimulating Factor-1 (CSF-1) is strongly pro-tumorigenic in most cancers, as the activation of the Colony Stimulating Factor-1 Receptor (CSF-1R) promotes the M2 polarization of TAMs." (PMID 39194679, 2024). "This revelation positions CSF1R as a key player in the broader cancer biology landscape and underscores its potential as a therapeutic target." (PMID 38992688, 2024). "Emactuzumab (RG7155), an anti-CSF1R monoclonal antibody, reduces the quantity and functional activity of TAMs in various cancer types and promotes CD8+ T cell infiltration." (PMID 39286635, 2024). "Cancer cell migration is a complex process involving different molecular components and evidence supports the role of CSF-1R in this process." (PMID 38254773, 2024). "The expression of CSF-1R in cancer cells has only recently been studied, and there is still a lot to learn regarding this research area." (PMID 38254773, 2024). "The diverse functions of the CSF-1R in regulating TAMs within the TME are crucial for understanding cancer progression and developing effective therapeutic strategies." (PMID 39457693, 2024). "Recently, CSF-1R expression was also detected in the cell membrane of cancer cells, where it plays an important role in supporting cancer progression." (PMID 38254773, 2024). "In DCs, the CSF-1R alters antigen-presenting capabilities, compromising immune surveillance against cancer cells." (PMID 39457693, 2024). "We furthermore show that IL-6 and M-CSF are strong drivers of increased abundance of immune incompetent CD14+ DC3s in the context of cancer and show that pharmacological inhibition of the IL-6R and CSF1R has potential to improve immunotherapy." (PMID 38242119, 2024). "Recently, CSF-1R expression was reported in the cell membrane of the cancer cells of different solid tumors, capturing the interest of various research groups interested in investigating the role of this receptor in non-myeloid cells." (PMID 38254773, 2024). "Preclinical studies have demonstrated that depleting TAMs using CSF-1R inhibitors can enhance the effectiveness of PD-1/PD-L1 blockades in various cancer models." (PMID 38791529, 2024). "In colorectal cancer (CRC), cancer cells secrete IL-34 and express CSF-1R, suggesting the presence of an autocrine positive feedback loop on the receptor." (PMID 38254773, 2024). "To this end, we first examined the publicly available AML data (gepia.cancer-pku.cn) and found that the CSF1R gene is overexpressed in many AML patient samples, similar to several other AML-implicated targets previously, FLT3, MLL and CDK6." (PMID 38641704, 2024). "For instance, CSF1R participates in modulating cancer stemness, the immunosuppressive microenvironment and metastasis in GC." (PMID 38425243, 2024). "CSF-1R mRNA is expressed in different cancer cell lines, and various studies reported that CSF-1R mRNA up-regulation correlated with poor prognosis in tumors." (PMID 38254773, 2024). "As such, the nanocarrier not only serves as an indispensable tool for probing CSF1R functions but also heralds a promising future in cancer treatment regimens." (PMID 38992688, 2024). "CSF-1R is recently recognized for its role in cancer cell proliferation in solid tumors, through cell cycle downstream signaling pathways, and is supported by the TGF-B immune suppression mechanism." (PMID 39796695, 2024). "IHC analysis of prostatic adenocarcinoma indicated that CSF-1R expression was higher in metastatic tissue compared to non-metastatic controls, and the receptor was expressed by both cancer and stromal cells." (PMID 38254773, 2024). "While no clinical trials are currently focusing on CSF1R inhibitors, particularly for bone metastasis treatment, several studies are exploring CSF1R inhibitors for various cancer types." (PMID 39148909, 2024).
cancer (continued). "Under standard conditions, CSF-1 is released by cancer cells as a soluble ligand which acts on macrophages via the CSF-1R in a paracrine and possibly endocrine fashion." (PMID 39194679, 2024). "Collectively, these experimental data validated the links a, b, and c proposed in our working model and demonstrated the effect of flutamide, via the expression of miR-449a and miR-449b-5p, on the suppression of CSF1R and AR and cancer cell migration." (PMID 39622842, 2024). "To date, several comprehensive review articles have been published on the use of CSF-1R inhibitors, antagonists, and monoclonal antibodies in cancer therapy." (PMID 39457693, 2024). "Overall, this study provides a more complete understanding of the potential benefit of antagonizing the CSF1/CSF1R pathway in combination with therapeutic cancer vaccines in breast and colon carcinoma models." (PMID 37505292, 2023). "Accumulating evidence demonstrated that IL-34 favors the differentiation of M2-phenotype macrophages in diverse cancers by binding to CSF1R." (PMID 37344903, 2023). "In the present study, our analysis has shown that CD276 expression was positively correlated with a number of immune checkpoint genes, including TGFBR1, TGFB1, NECTIN2, IL10RB and CSF1R, in most types of cancer." (PMID 36717836, 2023). "This is evident in the rejection of carcinogen-exposed DMBA3-4 cells mixed with control cancer cells, which is achieved by anti-CSF1R and anti-TIGIT combination treatment." (PMID 37843274, 2023). "Macrophage colony-stimulating factor (M-CSF) secreted by cancer cells binds to the colony-stimulating factor 1 receptor (CSF1R) on macrophages, which in turn activates downstream signaling pathways responsible for the M2 polarization of TAMs." (PMID 38159254, 2023). "Knowledge of the tissue-dependent metabolic effects of CSF1R inhibition is important in the development of immunomodulatory glucose-lowering drugs (e.g. liver-specific CSF1R inhibitors) or in the development of CSF1R inhibitors in cancer therapy." (PMID 37792013, 2023). "For this experiment, RFP-labeled B16F10 cancer cells were injected intravenously into MacGreen recipient mice that express eGFP under the control of the ​Csf1r​ promoter." (PMID 37426658, 2023). "Currently, few studies have investigated the combination of cancer vaccines with CSF1/CSF1R inhibition." (PMID 37505292, 2023). "As BT-474 cancer cells were reported to express CSF1R protein and mRNA, albeit at lower levels compared to M2-like macrophages, we tested for possible direct cytotoxic effects of CSF1Ri on BT-474 cells." (PMID 37346794, 2023). "The CSF1R signaling pathway is essential in the biology of the mononuclear/phagocyte system, which can promote the development of cancer." (PMID 37013652, 2023). "Other phase I and II studies involving blockade of the CSF-1/CSF1R pathway are underway in different types of cancers." (PMID 37143666, 2023). "Next, we explored macrophage and cancer cell viability following CSF1/CSF1R pathway inhibition and CD40L/CD40 pathway activation in the MTS for 4 and 7 days." (PMID 37346794, 2023). "Colony stimulating factor receptor 1 (CSF1R) is a critical macrophage proliferation marker that is currently being actively investigated in clinical trials as a therapeutic target in cancer." (PMID 37371076, 2023). "Altogether, these findings suggest prudence in the current trials of CSF1R inhibitors to deplete microglia in cancer or neurological conditions, and warrant the monitoring of potential off-target effects on myelin health." (PMID 36517604, 2023). "US clinical trials in cancer using Colony-stimulating factor 1 receptor (CSF-1R) blockade as intervention." (PMID 37114134, 2023). "For example, Colony-Stimulating Factor Receptor 1 (CSF1R) inhibitor was able to overcome PD-1/PD-L1 chemotherapy resistance in some cancers." (PMID 37693009, 2023). "The Colony-stimulating factor 1 receptor (CSF1R) is fast gaining traction in the realm of cancer therapeutics." (PMID 38035068, 2023).